CTSC (cathepsin C)
Description:
Thiol protease. Has dipeptidylpeptidase activity. Active against a broad range of dipeptide substrates composed of both polar and hydrophobic amino acids. Proline cannot occupy the P1 position and arginine cannot occupy the P2 position of the substrate. Can act as both an exopeptidase and endopeptidase. Activates serine proteases such as elastase, cathepsin G and granzymes A and B.
Synonyms: DPP-I; DPPI; CPPI; DPP1; HMS; JP; JPD; PALS; PDON1; PLS
Tractability: Small molecule: a drug acting on it is in phase 2 or 3 trials; a structure with a bound ligand is known; a high-quality ligand is known; it belongs to a druggable protein family. Antibody: its Gene Ontology location is reachable by antibodies, with high confidence; UniProt predicts a signal peptide or a membrane-spanning region. PROTAC: ubiquitination databases record sites on it; its protein half-life has been measured; a small molecule that binds it is known.
Target class: Cysteine protease; Cysteine protease CA clan; Enzyme; Protease; Cysteine protease C1A family
Chemical probes: BI-1750 (high quality), BI-9740 (high quality), CHEMBL3261920, CHEMBL3261926 (high quality)
Gene: Protein-coding gene on chromosome 11 (88,265,069 to 88,359,684, reverse strand). Ensembl gene ENSG00000109861.
Subcellular location: Lysosome
Subcellular location (Human Protein Atlas): Vesicles
Pathways (Reactome):
Immune System: MHC class II antigen presentation; Neutrophil degranulation
Vesicle-mediated transport: COPII-mediated vesicle transport; Cargo concentration in the ER
Gene Ontology:
Molecular function: cysteine-type peptidase activity; dipeptidyl-peptidase activity; protein binding; phosphatase binding; protein-folding chaperone binding; chloride ion binding; identical protein binding; peptidase activator activity involved in apoptotic process; serine-type endopeptidase activity
Biological process: proteolysis; immune response; positive regulation of protein catabolic process; apoptotic process; T cell mediated cytotoxicity
Cellular component: extracellular exosome; extracellular matrix; extracellular region; membrane; azurophil granule lumen; COPII-coated ER to Golgi transport vesicle; endoplasmic reticulum lumen; endoplasmic reticulum-Golgi intermediate compartment membrane; lysosome; cytoplasm
Genetic constraint (gnomAD): Loss-of-function variants: 29 observed, 37.63 expected, observed/expected ratio (o/e) 0.77, 90% interval 0.57 to 1.05. The upper end of that interval is the gene's LOEUF score, 1.05, which puts it in group 4 of 6, group 1 being the genes least tolerant of losing a copy. Missense variants: 580 observed, 545.1 expected, observed/expected ratio (o/e) 1.06, 90% interval 0.99 to 1.14. Synonymous variants: 227 observed, 195.28 expected, observed/expected ratio (o/e) 1.16, 90% interval 1.04 to 1.3.
Homologues: Orthologues: chimpanzee CTSC (99% identical), macaque CTSC (95% identical), rabbit CTSC (88% identical), pig CTSC (86% identical), guinea pig CTSC (83% identical), dog CTSC (83% identical), rat Ctsc (79% identical), mouse Ctsc (78% identical), zebrafish ctsc (63% identical), tropical clawed frog ctsc (61% identical), Caenorhabditis elegans cpr-1 (22% identical), Caenorhabditis elegans cpr-4 (22% identical), and 11 more. Paralogues in human: CTSB (23% identical), TINAGL1 (22% identical), CTSH (21% identical), CTSV (21% identical), TINAG (21% identical), CTSL (20% identical), CTSK (19% identical), CTSZ (19% identical), CTSS (19% identical), CTSF (19% identical), CTSW (19% identical), CTSO (17% identical).
Diseases named in the same sentence as CTSC in open-access papers:
CTSC is named in the same sentence as 114 diseases in open-access papers, as found by Europe PMC text mining. Sharing a sentence is not in itself a finding about the gene and the disease. The quoted sentences say what the papers report.
breast cancer (34 papers, 2006 to 2025). A primary or metastatic malignant neoplasm involving the breast. "On the other hand, increased cathepsin C activity and expression in tumor (and associated) cells of all breast cancer subtypes does make this protease a promising target for imaging of lung metastases." (PMID 36002710, 2023). "For instance, CTSC can facilitate the seeding of metastatic breast cancer to the lungs by mediating neutrophil infiltration and the formation of neutrophil extracellular traps, which are implicated in breast cancer dissemination." (PMID 40299531, 2025). "Cathepsin C (CTSC) has been identified as a critical factor secreted by lung-tropic breast cancer cells that promotes neutrophil recruitment and NET formation at premetastatic sites." (PMID 41463352, 2025). "In breast cancer, tumor-secreted cathepsin C enhances neutrophil recruitment and NET formation via inflammatory pathways such as the PR3–IL–1β–NF–κB axis, thereby promoting lung metastasis." (PMID 41303697, 2025). "In the context of cancer, studies have shown that cathepsin C secreted by breast cancer cells promotes lung metastasis by regulating neutrophil recruitment and NET formation." (PMID 41303697, 2025). "Recent studies reveal that breast cancer-derived cathepsin C (CTSC) activates neutrophil membrane protease 3 (PR3), triggering Interleukin-1β (IL-1β)/nuclear factor-kB (NF-κB) signaling cascades through pro-IL-1β cleavage." (PMID 40568594, 2025). "In breast cancer, the tumor-secreted protease cathepsin C promotes breast-to-lung metastasis by regulating the recruitment of neutrophils and the formation of neutrophil extracellular traps." (PMID 39123434, 2024). "In a study on breast cancer, researchers found that the tumor-secreted protease cathepsin C (CTSC) promotes breast cancer lung metastasis by affecting the infiltration of neutrophils." (PMID 38862250, 2024). "To summarize, in breast cancer, cathepsin C holds a specialized role during the early stages of pulmonary colonization." (PMID 36002710, 2023). "In human cell lines derived from primary and metastatic tumors and in tissue samples of different molecular breast cancer subtypes, significantly higher cathepsin C levels in lung metastases than in primary breast tumors were observed." (PMID 36002710, 2023). "CTSC enzymes released by breast cancer cells can control NET development, thus promoting lung metastasis of breast cancer." (PMID 37868992, 2023). "In previous studies, CTSC was considered a key molecule in squamous cell carcinoma as well as breast cancer." (PMID 37006257, 2023). "The latest research has discovered that Cathepsin C promotes breast cancer lung metastasis by modulating neutrophil infiltration and neutrophil extracellular trap formation." (PMID 37450415, 2023). "CTSC levels are highly increased in metastases compared to the primary tumors of breast cancer patients." (PMID 37350937, 2023). "A recent study revealed that cathepsin C derived from breast cancer promotes lung metastasis by modulating neutrophil infiltration and the formation of neutrophil extracellular traps." (PMID 37789385, 2023). "Cathepsin C, derived from breast cancer cells, promoted lung metastasis of breast cancer cells by regulating neutrophil infiltration and the formation of NETs in lungs metastasis microenvironment." (PMID 35719975, 2022). "Regulation of NETs formation in lung metastasis of breast cancer has recently been reported by tumor-secreted proteins Cathepsin C or lung mesenchymal stromal cells produced complement 339,40." (PMID 36253427, 2022). "Previous studies have shown that CTSC is upregulated in a variety of malignant tumors, including squamous cell carcinoma, pancreatic cancer, and breast cancer." (PMID 35109832, 2022). "Tumor‐secreted protease cathepsin C (CTSC) activity also enhances breast cancer metastasis through recruitment of neutrophils and formation of NETs." (PMID 35506376, 2022).
breast cancer (continued). "Although previous studies indicated that CTSC expression is up-regulated in several tumor cells, such as pancreatic cancer, hepatocellular carcinoma and breast cancer, its relationship between aging and gliomas is unclear." (PMID 33946049, 2021). "One example is the tumor-secreted protease cathepsin C, CTSC, that have a role in promoting lung colonization of breast cancer inducing neutrophil-mediated NETs to the metastatic site." (PMID 34261496, 2021). "It was reported recently that CTSC (cathepsin C) secretion promoted lung metastasis of breast cancer via facilitating neutrophils extracellular traps (NETs) formation." (PMID 34830862, 2021). "Additionally, breast cancer cell-secreted cathepsin C (CTSC) induces neutrophil production of ROS and NETs via the CTSC-PR3-IL-1β axis, leading to thrombospondin-1 (THBS1) degradation and reduced endothelial adhesion, ultimately facilitating lung metastasis." (PMID 40568594, 2025). "Moreover, CTSC regulates breast cancer lung metastases by modulating neutrophil infiltration and the formation of neutrophil extracellular traps." (PMID 38742112, 2024). "Xiao and colleagues found that the CTSC could promote lung metastasis of breast cancer through mediating recruitment of neutrophils and formation of neutrophil extracellular traps based on the CTSC/PR3/IL-1β axis." (PMID 36276992, 2022). "Administration of the CTSC inhibitor, AZD7986, effectively inhibited breast cancer metastasis to the lung in a mouse model." (PMID 41019086, 2025). "An additional protein family of interest is the CTS proteins; in the present study, five CTS proteins (CTSB, CTSC, CTSD, CTSH and CTSZ) were identified to be upregulated in breast cancer." (PMID 24932247, 2014). "We also compared the expression intensities of PRSS23, CTSC, CTSF, and MMP-24 from 52 ERα-positive breast cancer specimens within the van't Veer dataset." (PMID 22291950, 2012). "Tumor-secreted protease cathepsin C (CTSC) also acts on neutrophils by activating neutrophil membrane binding proteinase 3 (PR3), promoting the production of NETs and thus promoting lung metastasis of breast cancer cells." (PMID 37373412, 2023). "Similarly, high expression of the cathepsin family of proteases (CTSC, CTSZ, CTSB) was found to be indicative of poor prognosis in breast cancer patients but appeared to have no significant predictive value in prostate cancer patients." (PMID 17183660, 2006).
periodontitis (23 papers, 2013 to 2025). An acute or chronic inflammatory process that affects the tissues that surround and support the teeth. "For example, a number of papers consistently reported on a variant in the CTSC gene in association with non‐syndromic early onset periodontitis." (PMID 40197750, 2025). "PLS is also a rare autosomal recessive disease with typical signs of PPK and severe early-onset periodontitis; onset usually occurs between 1–4 years old, and mutations in the cathepsin C gene (CTSC) have been reported to be related to the pathogenesis of PLS." (PMID 37393290, 2023). "Deficiency of CTSC in mammals leads to the development of autoimmune diseases such as periodontitis, Halm-Munk syndrome, and Papillon-Lefevre syndrome." (PMID 37576559, 2023). "The CTSC gene that code cathepsin C, is commonly expressed in epithelial cells and causes different clinical symptoms such as severe gingivostomatitis and periodontitis." (PMID 33586345, 2021). "The PLS individuals of this study had a genetic predisposition of ineffective cathepsin C that led to inflammation and stage IV periodontitis, which suits the inflammation-mediated plymicrobial-emergence and dysbiotic exacerbation (IMPEDE) model." (PMID 34513733, 2021). "It has been suggested that cathepsin C gene variants contribute to increased susceptibility in generalized aggressive periodontitis." (PMID 24949444, 2014). "PLS is caused by different mutations in the CTSC gene resulting in typical and atypical pathological outcomes, including those with isolated keratosis and periodontitis." (PMID 25260376, 2014). "Moreover, there are a few dental clinics in the United States that offer genetic testing for aggressive periodontitis (AP) and Sjogren’s syndrome by testing mutations in Cathepsin C (CTSC), LYST, COL5A1, FcyIIB, and FPRI for AP." (PMID 40136761, 2025). "Likewise, patients with Papillon–Lefevre syndrome and Haim–Munk syndrome develop periodontitis due to the low levels of LL-37 caused by lost-of-function mutations in the cathepsin C (CTSC) gene." (PMID 36294968, 2022). "Mutations in the cathepsin C gene have been identified in prepubertal aggressive periodontitis." (PMID 24949444, 2014). "Genetic testing shows promise for rare, severe, single-gene, early-onset forms of periodontitis, such as those linked to mutations in the CTSC gene (cathepsin C), causing conditions like Papillon–Lefevre syndrome." (PMID 41300760, 2025). "The Papillon–Lefèvre syndrome (PLS) is a rare autosomal recessive disorder caused by mutations in the Cathepsin C (CTSC) gene, characterized by periodontitis and palmoplantar hyperkeratosis." (PMID 33445524, 2021). "PLS is a rare autosomal recessive disease in which DPP1 insufficiency, which is caused by a mutation in the DPP1 gene (CTSC), results in diffuse palmoplantar hyperkeratosis, severe prepubertal periodontitis, and premature loss of both deciduous and permanent teeth." (PMID 38162644, 2023). "Although it has been associated with functional defects in neutrophils, the mechanisms by which CTSC deficiency leads to periodontitis have not been fully elucidated so far." (PMID 32625202, 2020). "Moreover, patients with Papillon-Lefèvre syndrome (PLS), characterized by mutations that inactivate Cathepsin C, a cysteine protease that processes ELANE into its active state, develop severe periodontitis." (PMID 32243431, 2020). "The association between Cathepsin C gene alterations and susceptibility of PLS patients to periodontitis may be explained by the role of Cathepsin C gene in influencing epithelial differentiation or desquamation." (PMID 26523234, 2015). "Cathepsin C is the enzyme whose activity decreases in periodontitis." (PMID 24949444, 2014). "Additionally, the CTSC gene, mutations of which are responsible for aggressive periodontitis in juveniles, was found to be widely expressed in the nonimmune cell population." (PMID 34566966, 2021).
periodontitis (continued). "Therefore, studies investigating the activity together with the levels of cathepsin C enzyme in generalized aggressive and chronic types of periodontitis and gingivitis would be useful for analyzing the role of this enzyme in the pathogenesis of periodontal diseases." (PMID 24949444, 2014). "Cathepsin C activity has been found to be significantly lower in tissue extract supernatants and gingival crevicular fluid (GCF) of periodontitis patients compared with those of healthy controls." (PMID 24949444, 2014). "Here, cathepsin C plays a central role as seen in Papillon–Lefèvre syndrome in humans, where a lack of cathepsin C expression impairs neutrophil function, giving rise to erythematous palmoplantar hyperkeratosis and early-onset periodontitis." (PMID 34918208, 2022). "In oral fluids such as saliva and GCF from PLS subjects, the CTSC activity was most absent or detected at very low levels in comparison to the activity in other periodontitis patients and even the periodontally healthy subjects." (PMID 25260376, 2014). "Indeed, in periodontitis patients without known genetic disorders the load of P. gingivalis and the other proteolytic periodontopathogens is correlated with activity of CTSC, NE and PR3 and the released α-defensins and mature LL-37." (PMID 25260376, 2014). "However, heterozygous family members showing a reduced cathepsin C activity were not affected by periodontitis." (PMID 24949444, 2014). "Mechanistically, deficient activation of leukocyte serine proteinases due to lack of cathepsin C gene activity could possibly explain the severe periodontitis in PLS." (PMID 24303219, 2013). "Researchers stated that cathepsin C activity was significantly lower in diseased samples compared to healthy samples for GCF, and cathepsin C might be involved in adult periodontitis patients not suffering from PLS." (PMID 24949444, 2014).
Papillon-Lefèvre syndrome (18 papers, 2010 to 2024). "Papillon-Lefevre syndrome (PLS) manifests as an autosomal recessive disorder caused by a mutation in the cathepsin C (CTSC) gene." (PMID 37701012, 2023). "Papillon-Lefèvre Syndrome (PLS) is an autosomal recessive monogenic disease caused by loss-of-function mutations in the CTSC gene, thus preventing the synthesis of the protease Cathepsin C (CTSC) in a proteolytically active form." (PMID 34932608, 2021). "Subsequently, inactivating mutations were identified in this gene and an almost total loss of cathepsin C activity was shown in patients with Papillon-Lefèvre syndrome." (PMID 24303219, 2013). "Papillon-Lefèvre Syndrome (PLS) is a type IV genodermatosis caused by mutations in cathepsin C (CTSC), with a worldwide prevalence of 1–4 cases per million in the general population." (PMID 23311634, 2013). "Recently, germline mutations in the lysosomal protease cathepsin C gene have been identified as the underlying genetic defect in Haim-Munk syndrome and in the clinically related disorders, such as Papillon-Lefèvre syndrome and prepubertal periodontitis." (PMID 21760678, 2010). "Recently identified genetic defect in PLS has been mapped to chromosome 11q14–q21, which involves mutations of cathepsin C. This paper presents a report of 2 cases of Papillon-lefevre syndrome in which diagnosis is based on clinical presentation and genetic mapping." (PMID 24303219, 2013). "However, the absence of active HNE in PMN is tolerated, as seen in people with the congenital cathepsin C deficiencies Haim-Munck and Papillon-Lefèvre syndrome, in the clinical use of the HNE inhibitors alvelestat and sivelestat, and in clinical trials of novel cathepsin C inhibitors." (PMID 39063160, 2024). "Papillon-Lefèvre Syndrome (PLS) is an autosomal recessive disorder that is caused by mutations in cathepsin C (CTSC) (OMIM #245000)." (PMID 23311634, 2013). "An almost completed depletion of proinflammatory elastolytic enzymes was described in neutrophils from patients with Papillon-Lefèvre syndrome (PLS), a disease characterized by cathepsin C (CatC) deficiency." (PMID 35163482, 2022). "Not only in mouse, but also in humans with Papillon-Lefèvre syndrome, marked by severe reduction in cathepsin C activity, cytotoxic cells display adequate killing ability." (PMID 31555270, 2019). "Cathepsin C is also needed for processing serine protease cathepsin G in neutrophils, and Papillon-lefevre syndrome patients may suffer from the consequences of neutrophil dysfunction." (PMID 31555270, 2019). "The absence of cathepsin C is found to be related to a diminished activity of the PMN-derived proteases in patients with Papillon-Lefevre syndrome (PLS)." (PMID 24949444, 2014).
bronchiectasis (17 papers, 2019 to 2025). Segmental, irreversible dilation of the bronchial tree resulting in the accumulation of secretions which leads to obstruction. "Airleaf is a phase 2 study investigating the efficacy, safety and dosing of BI 1291583, a novel cathepsin C inhibitor, in bronchiectasis." (PMID 37465817, 2023). "Inhibition of cathepsin C (CatC) activity has the potential to decrease activation of neutrophil-derived serine proteases in patients with bronchiectasis, thereby reducing airway inflammation, improving symptoms, reducing exacerbations and preventing further airway damage." (PMID 37465817, 2023). "The cathepsin C inhibitor INS1007, originally developed by AstraZeneca as AZD7986, an orally applicable drug, is currently assessed in bronchiectasis patients over a 24 week treatment period (ClinicalTrials.gov Identifier: NCT03218917)." (PMID 31289357, 2019). "As cathepsin C (CatC; also known as dipeptidyl peptidase 1) activates NSPs in the bone marrow during myelopoiesis, CatC inhibition is expected to reduce NSP activity in the lungs of patients with bronchiectasis, thereby restoring the protease/antiprotease balance." (PMID 38529344, 2024).